HDAC4 (histone deacetylase 4)
Diseases named in the same sentence as HDAC4 in open-access papers (continued):
Sharing a sentence is not in itself a finding about the gene and the disease.
mental disorder (3 papers, 2016 to 2022). A disease that has its basis in the disruption of mental process. "Therefore, the role of HDAC4 in cognitive function, its dysregulation in cognitive impairment-related neurodegenerative diseases and mental disorders, and underlying mechanisms are discussed in this review." (PMID 27847464, 2016). "Moreover, aberrant expression of HDAC4 may be implicated in the cognitive impairment of neurodegenerative diseases and mental disorders." (PMID 27847464, 2016). "Accumulated evidence shows that HDAC4 expression is dysregulated in several brain disorders, including neurodegenerative diseases and mental disorders." (PMID 27847464, 2016). "Increased evidence indicates that aberrant HDAC4 expression or function plays an important role in cognitive deficits of mental disorders." (PMID 27847464, 2016).
myocardial ischemia (3 papers, 2013 to 2024). A disorder of cardiac function caused by insufficient blood flow to the muscle tissue of the heart. "In addition, myocardial ischemia and reperfusion injury demonstrates an over-expression of HDAC4 in the heart caused by the reduction in anti-oxidant enzymes (SOD) and increase in apoptosis, which were prevented by TSA treatment." (PMID 30134825, 2018). "Taken together, these findings are the first to define that activated HDAC4 as a crucial regulator for myocardial ischemia and reperfusion injury." (PMID 30134825, 2018). "We used cardiomyocyte-specific overexpression of active HDAC4 to determine the functional role of activated HDAC4 in regulating myocardial ischemia and reperfusion in isovolumetric perfused hearts." (PMID 30134825, 2018). "There is no information to define the role of activated HDAC4 in in mediating cardiac ischemia and reperfusion injury." (PMID 30134825, 2018).
Ovarian Tumors (3 papers, 2020 to 2024). "Recent studies show that HDAC4-HIF1α axis as is an important signal pathway regulating glycolysis, apoptosis and autophagy in ovarian tumor cells during hypoxic adaptation." (PMID 37149664, 2023). "Higher-grade ovarian tumors exhibit downregulation of HDAC4." (PMID 39063083, 2024).
retinal degeneration (3 papers, 2014 to 2022). Degeneration of the retina. "HDAC4 overexpression in a mouse model of retinal degeneration prolonged photoreceptor survival, which was attributed to the activity of HDAC4 in the cytoplasm and at least partly relied on the activity of HIF-1α." (PMID 34057022, 2021). "Recently, acetylation of retinal histones was found to increase inflammation in diabetic retinopathy, and overexpression of histone deacetylase 4 (HDAC4) was found to promote neuronal survival and protect against retinal degeneration." (PMID 24416337, 2014).
rhabdomyosarcoma (3 papers, 2012 to 2021). A rare aggressive malignant mesenchymal neoplasm arising from skeletal muscle. "Moreover, the specific genetic silencing of HDAC4 leads to up-regulation of miR-206 in rhabdomyosarcoma, which is an aggressive soft-tissue cancer characterized by disturbed myogenic differentiation, indicating that miR-206 is specifically regulated by HDAC4." (PMID 34526481, 2021).
subarachnoid hemorrhage (3 papers, 2021 to 2024). A serious neurological disorder characterized by intracranial hemorrhage into the subarachnoid space. "Inhibition of HDAC4 attenuates neuronal apoptosis via reduction of JNK/c-Jun activity during early brain injury following subarachnoid hemorrhage." (PMID 34526481, 2021).
acrodysostosis (2 papers, 2018 to 2023). Acrodysostosis (ACRDYS) is a rare primary bone dysplasia characterized by severe brachydactyly, peripheral dysostosis with facial dysostosis, nasal hypoplasia, and developmental delay. "However, unlike PRMT7-related disorder, these are all autosomal dominant disorders caused by heterozygous variants in GNAS (PHP 1A and 1C), PRKAR1A and PDE4D (acrodysostosis), and/or 2q37 deletion resulting in loss of the HDAC4." (PMID 36399134, 2023).
acute kidney injury (2 papers, 2025). Sudden and sustained deterioration of the kidney function characterized by decreased glomerular filtration rate, increased serum creatinine or oliguria. "In induced acute kidney injury (AKI) model, berberine conferred renoprotection by regulating the histone deacetylase 4 (HDAC4)-FoxO3a axis to induce autophagy and inhibit apoptosis." (PMID 41050400, 2025). "Histone deacetylase 4 (HDAC4) modifies both histone and non-histone proteins, but its role in the transition from acute kidney injury (AKI) to chronic kidney disease (CKD) remains unclear." (PMID 41282137, 2025).
acute lymphoblastic leukemia (2 papers, 2016 to 2017). Leukemia with an acute onset, characterized by the presence of lymphoblasts in the bone marrow and the peripheral blood. "Recently, Gruhn and his colleagues found that high HDAC4 expression is associated with poor survival, high initial leukocyte count, T cell ALL and prednisone poor-response in childhood acute lymphoblastic leukemia." (PMID 27295551, 2016). "In T cell acute lymphoblastic leukemia (ALL) patients, hyperexpression of HDAC4 is correlated with a higher initial count of leukocytes and poor response to prednisone." (PMID 28177888, 2017).
Albright hereditary osteodystrophy (2 papers, 2005 to 2023). "In this study a critical interval for brachymetaphalangism, which is the main symptom of Albright hereditary osteodystrophy (AHO)-like brachymetaphalangism, has been assigned to the 3 Mb region from HDAC4 gene to the telomere." (PMID 15904506, 2005).
autism spectrum disorder (2 papers, 2019 to 2021). A spectrum of developmental disorders that includes autism, and Asperger syndrome. "HDAC4 is associated with risks of autism spectrum disorder, neuronal cell survival, synaptic plasticity, and memory depression." (PMID 34638996, 2021).
bladder (2 papers, 2011 to 2017). "The results of our IHC studies reveal that the frequency of the HDAC4-positive tissue specimens was significantly increased in the urinary bladder transitional cell carcinomas in comparison to normal bladder tissues." (PMID 21507255, 2011).
brain cancer (2 papers, 2022 to 2024). A primary or metastatic malignant neoplasm affecting the brain. "HDAC4 protein stimulates IFNγ (Type 2 interferon signaling) and HDAC inhibition is considered a potential therapeutic strategy in pediatric brain cancers." (PMID 36293188, 2022).
brain tumor (2 papers, 2019 to 2022). "In addition, a study of the tissue distribution of HDACs indicated that the expression of HDAC4 was increased in brain tumors compared to normal brain tissue." (PMID 36139696, 2022).
cardiomyopathy (2 papers, 2013 to 2019). A disease of the heart muscle or myocardium proper. "A large number of important transcription factors or regulators implicated in cardiomyopathy have been identified as bona-fide targets of miR-22, including Purb, Hdac4, Ppara, Sirt1, and Pgc1a." (PMID 24086656, 2013).
cervical carcinoma (2 papers, 2020 to 2022). A carcinoma arising from either the exocervical squamous epithelium or the endocervical glandular epithelium. "As for the probe cg27012396 near a functional gene HDAC4, various publications have confirmed that HDAC4 regulates the glycolysis and survival of hypoxic tumor cells in cervical carcinoma." (PMID 36249027, 2022). "As for biomarkers for cervical carcinoma, cg27012396 and its functional gene HDAC4 were confirmed to regulate the glycolysis and survival of hypoxic tumor cells in cervical carcinoma." (PMID 36249027, 2022).
cholangiocarcinoma (2 papers, 2015 to 2024). A carcinoma that arises from the intrahepatic biliary tree (intrahepatic cholangiocarcinoma) or from the junction, or adjacent to the junction, of the right and left hepatic ducts (hilar cholangiocarcinoma). "Taken together, these data suggest that TGF-β1-mediated miR-29a inhibition may contribute to cholangiocarcinoma cell proliferation and metastasis, which are partly associated with HDAC4-induced EMT." (PMID 26441331, 2015). "In a previous study, TGF-β1 was reported to reduce miR29a expression, promoting tumorigenicity and metastasis of cholangiocarcinoma by upregulating HDAC4." (PMID 38473392, 2024). "Our data provide novel insight into the mechanism of TGF-β1/miR-29a/HDAC4 pathway in the pathogenesis of cholangiocarcinoma and provide new therapeutic targets for cholangiocarcinoma." (PMID 26441331, 2015). "Our findings will help to elucidate the roles of TGF-β1/miR-29a/HDAC4 in the pathogenesis of cholangiocarcinoma and provide new therapeutic targets." (PMID 26441331, 2015). "It is suggested that, the increased level of TGF-β1 in cholangiocarcinoma is responsible for the inhibition of miR-29a,followed by the activation of HDAC4 signaling, which may in turn promote EMT." (PMID 26441331, 2015). "We next determined the biological role of HDAC4 in cholangiocarcinoma cells." (PMID 26441331, 2015). "Furthermore, miR-29a inhibited cholangiocarcinoma cell growth and metastasis by targeting HDAC4." (PMID 26441331, 2015).
cholestasis (2 papers, 2015 to 2023). Impairment of the bile flow caused by obstruction within the liver, or outside the liver in the bile duct system. "We then treated primary HSCs with one of the hydrophobic bile acids, taurolithocholic acid (TLCA; Sigma), to explore whether miR-29a affects HDAC4 expression and nuclear translocation in response to cholestasis." (PMID 26305546, 2015). "Moreover, miR-29a overexpression significantly downregulated HDAC4 immunoreactivity in miR-29aTg mice with cholestasis compared with the WT littermates (p < 0.001), indicating that miR-29a might have an impact on HDAC4 expression in early cholestasis." (PMID 26305546, 2015).
chronic heart failure (2 papers, 2014 to 2025). "The congestive heart failure-associated targets were Dnmt1, Hdac1, Hdac4, Ezh2, Sirt3, Kdm2a, Prkca and Prkcb (9.8% of total targets)." (PMID 40076868, 2025).
cognitive decline (2 papers, 2016 to 2019). "A large body of evidence indicates that aberrant HDAC4 expression and subcellular distribution may contribute to the cognitive decline in patients with neurodegenerative diseases." (PMID 27847464, 2016). "Above evidence suggests that alteration of HDAC4 may contribute to cognitive decline in patients with PD." (PMID 27847464, 2016).
congenital heart defects (2 papers, 2023 to 2024). "The 2q37.3 deletion is a P CNV that involves the 2q37.3 terminal region (including the HDAC4 gene), and the main clinical manifestations in the neonatus were congenital anorectal malformation, congenital heart disease, and mild ventriculomegaly." (PMID 38336695, 2024).
dementia (2 papers, 2016 to 2021). Loss of intellectual abilities interfering with an individual's social and occupational functions. "Together, these data are strong evidence that the nuclear translocation of HDAC4 in hippocampal pyramidal cells is an early event in the onset of dementia of the Alzheimer’s type." (PMID 27022623, 2016).
dilated cardiomyopathy (2 papers, 2017 to 2025). Cardiomyopathy which is characterized by dilation and contractile dysfunction of the left and right ventricles. "Interestingly, the loss of miR-22 (which targets HDAC4) led to the development of dilated cardiomyopathy under stress conditions." (PMID 28662206, 2017).
disc degeneration (2 papers, 2021 to 2024). "In an IDD mouse model, GSK3β was downregulated in intervertebral disc tissues, and upregulating GSK3β mitigated NP cell apoptosis and disc degeneration in IDD mice by repressing HDAC4." (PMID 38217540, 2024). "HDAC4 overexpression aggravated the pain of disc degeneration." (PMID 33691773, 2021).
esophageal squamous cell carcinoma (2 papers, 2016 to 2024). Esophageal squamous cell carcinoma (ESCC) is a type of esophageal carcinoma (EC) that can affect any part of the esophagus, but is usually located in the upper or middle third. "Additionally, HDAC4 was overexpressed in esophageal squamous cell carcinoma (ESCC), where its overexpression was closely linked to increased tumor grade, advanced clinical stage and unfavorable survival outcomes." (PMID 38702756, 2024). "We found that HDAC4 mRNA and protein are overexpressed in esophageal squamous cell carcinoma (ESCC) tissues and cell lines." (PMID 27295551, 2016).
Glomerular sclerosis (2 papers, 2022 to 2023). Accumulation of scar tissue within the glomerulus. "DTsiANp/HDAC4 is designed to delivery HDAC4 siRNA to the podocytes in DKD rat model, after four weeks treatment, the glucose level, urinary albumin excretion ratio (UAER), MCs proliferation and glomerular sclerosis are all reduced significantly." (PMID 36576203, 2023).
inflammatory bowel disease (2 papers, 2022 to 2024). A spectrum of small and large bowel inflammatory diseases of unknown etiology. "Furthermore, in vitro investigations presented that HDAC4 negatively regulated the polarization of Th17 cells in naïve CD4+ T cells of patients with AS, which was in line with a previous study focusing on inflammatory bowel disease." (PMID 35602496, 2022).
liver disease (2 papers, 2017 to 2021). "Our findings as summarized in this report reveal a novel mechanism whereby HDAC4 contributes to hepatic disorders." (PMID 28548935, 2017). "Ultimately, class IIa HDAC4 and HDAC5, as key metabolic elements, represent a regulatory interface between genetic and metabolic factors affecting the varied phenotypic presentations and liver disease manifestations in WD." (PMID 34098115, 2021). "The main findings of our study are as follows: First, decreased HDAC4 and HDAC5 levels were identified in livers of tx-j mice starting at early stages of hepatic copper accumulation and progressing with age-related worsening of liver disease." (PMID 34098115, 2021).
lymph node metastasis (2 papers, 2022 to 2024). "In our study, not only lower HDAC-4 but also lower HDAC-2 expression was associated with the presence of lymph node metastasis." (PMID 38790909, 2024). "HDAC4 expression was positively correlated with lymph node metastasis (P = 0.005), tumour, node, metastasis (TNM) stage (P = 0.002), and depth of invasion (P = 0.001)." (PMID 35637410, 2022). "The presence of a similar association between HDAC-2 and -4 and lymph node metastasis is interesting, especially since there was not any significant association between HDAC-2 and HDAC-4." (PMID 38790909, 2024). "HDAC-4 expression was mostly correlated with clinicopathological parameters, being associated with lower FIGO stage and tumor T-category as well as the absence of lymph node metastasis or distant metastasis." (PMID 38790909, 2024).
memory impairment (2 papers, 2013 to 2023). "As one of class IIa HDACs, HDAC4 is expressed throughout the body with enrichment in the brain and relates closely to brain development, neuronal cell death, memory impairment, and neurodegeneration." (PMID 37190635, 2023). "MB247-driven expression of HDAC4 also impaired LTM, therefore MB-specific overexpression of HDAC4 is the likely root of the memory impairment." (PMID 24349558, 2013).
neuronal intranuclear inclusion disease (2 papers, 2015 to 2021). Neuronal intranuclear inclusion disease (NIID) is a very rare multisystem neurodegenerative disorder characterized by the presence of eosinophilic intranuclear inclusions in neuronal and glial cells, and neuronal loss. "The N-terminal domain of HDAC4 is a highly conserved glutamine-rich sequence that has been widely observed to increase the formation of aggregates with other proteins in human neurodegenerative diseases, such as Lewy Bodies, α-synuclein, and neuronal intranuclear inclusion disease (NIIND)." (PMID 34445342, 2021).
pulmonary arterial hypertension (2 papers, 2019 to 2022). Pulmonary arterial hypertension (PAH) is a group of diseases characterized by mean pulmonary artery pressure >20 mmHg and elevated pulmonary arterial resistance leading to right heart failure. "There were significant relationships between HDAC4 and two specific types of pulmonary hypertension: familial primary pulmonary hypertension and idiopathic pulmonary arterial hypertension." (PMID 35740428, 2022). "In contrast, increased expression of HDAC3, HDAC4, and HDAC5 is associated with induction of Nox2 and Nox4 in pulmonary arterial hypertension, which was decreased by the HDAC inhibitor, valproic acid." (PMID 31223486, 2019).
skin aging (2 papers, 2021 to 2022). The gradual irreversible changes in structure of skin that occur as a result of the passage of time.. "Collectively, HDAC4 and HDAC11 were decreased in both UV-irradiated and intrinsically aged skin, suggesting that they may play a universal role in increased histone acetylation associated with skin aging." (PMID 33670779, 2021). "Further research is warranted to assess the role of HDAC4 and HDAC11 in skin aging." (PMID 33670779, 2021).
squamous cell carcinoma (2 papers, 2013 to 2015). A carcinoma arising from squamous epithelial cells. "Looking broadly across all cancers, our results highlight that EZH2 is active in more primitive cancers of childhood, and HDAC4 is active in more mature adenocarcinomas and squamous cell carcinomas." (PMID 24079712, 2013).
Ureteral obstruction (2 papers, 2022). Obstruction of the flow of urine through the ureter. "Our recent studies showed that all the class IIa HDAC isoforms are expressed in the kidney, with HDAC4 being more abundant in renal tubular cells after unilateral ureteral obstruction; blocking class IIa HDACs with MC1568 exhibited an anti-fibrotic effect." (PMID 35935816, 2022). "We assessed the role of HDAC4 and possible mechanisms of fibrosis in a murine model of kidney injury induced by unilateral ureteral obstruction (UUO) using tasquinimod, a highly selective HDAC4 inhibitor, and knockout mice with depletion of HDAC4 in renal tubular cells." (PMID 35847036, 2022).
adenovirus infection (1 paper, 2022). "We found that m-HDAC4 was located in the chondrocyte nuclei, while HDAC4 was located in the cytoplasm of chondrocytes, as indicated by green fluorescence at 24 h after adenovirus infection of the cells." (PMID 34980076, 2022).
aging (1 paper, 2022). A developmental process that is a deterioration and loss of function over time. "It has been reported that DDIT4 is associated with senescence, and our previous studies demonstrated that HDAC4 might be a key regulator of skin aging." (PMID 35680564, 2022).
Airway obstruction (1 paper, 2014). Obstruction of conducting airways of the lung. "Taken together, these findings suggest that HDAC4 expression is likely to be upregulated in the muscles of patients with relatively preserved body composition and muscle mass, regardless of the airway obstruction." (PMID 25013984, 2014).
alcoholic cirrhosis (1 paper, 2024). "Hypermethylated DMRs observed in alcoholic cirrhosis and alcoholic HCC were found in forkhead box K1 (FOXK1), zinc finger CCCH-type containing 3 (ZC3H3), nuclear factor IX (NFIX), histone deacetylase 4 (HDAC4), and tetraspanin 9 (TSPAN9) genes." (PMID 38302914, 2024).
ankylosing spondylitis (1 paper, 2022). An autoimmune chronic inflammatory disorder characterized by inflammation in the vertebral joints of the spine and sacroiliac joints. "This study aimed to further investigate the correlation between HDAC4 and Th cells, inflammation, disease activity, and treatment response in patients with ankylosing spondylitis (AS)." (PMID 35602496, 2022).
Arthritis (1 paper, 2017). Inflammation of a joint. "In synovial fibroblasts from arthritis patients, HDAC1 siRNA enhanced TNFα-induced MMP-1 expression, whereas HDAC4 was identified as a negative regulator of MMP-1 expression." (PMID 28596772, 2017).
astrocytomas (1 paper, 2008). "Seven of 8 class II HDAC genes (exception for HDAC4) were expressed at lower levels in high-grade astrocytomas compared to low-grade astrocytomas (p < 0.05)." (PMID 18713462, 2008).